RNU6-717P (RNA, U6 small nuclear 717, pseudogene)
Gene: Small nuclear RNA gene on chromosome 12 (133,238,335 to 133,238,438, reverse strand). Ensembl gene ENSG00000239190.
Homologues: Orthologues: chimpanzee U6 (99% identical). Paralogues in human: RNU6-26P (83% identical), RNU6-166P (82% identical), RNU6-19P (82% identical), RNU6-45P (82% identical), RNU6-558P (82% identical), RNU6-843P (82% identical), RNU6-949P (82% identical), RNU6-1024P (81% identical), RNU6-1060P (81% identical), RNU6-1181P (81% identical), RNU6-1273P (81% identical), RNU6-12P (81% identical), and 1283 more.